NF2 (NF2, moesin-ezrin-radixin like (MERLIN) tumor suppressor)
Diseases named in the same sentence as NF2 in open-access papers (continued):
Sharing a sentence is not in itself a finding about the gene and the disease.
tumor (716 papers, 1994 to 2026). "Neurofibromatosis type 2 (NF2) emerged as the top tumor suppressor, whose loss enhances PDAC malignancy." (PMID 41480769, 2026). "FASN protein is frequently detected in NF2/p16-deficient PM tumor-derived tissues (15/15, 100%), but rarely in NF2/p16-intact PM tumors (8/25, 32%)." (PMID 41764192, 2026). "Matrix metalloproteinase-9 (MMP-9) is a key protease involved in extracellular matrix remodeling and tumor progression in NF2-associated VS, making it an attractive molecular target for activity-based sensing." (PMID 41675655, 2026). "As expected, DHODH inhibition significantly suppressed tumor growth and reduced Ki-67-positive cells in NF2-deficient tumors, while having minimal effects on wild-type tumors." (PMID 40707702, 2025). "NF2 mutations are typically confined to tumor cells, leading to unilateral and sporadic VS in over 90% of cases, with an incidence of 1:10,000." (PMID 39923035, 2025). "We identified a pathogenic heterozygous deletion of NF2 in blood DNA and the concomitant loss of the NF2 locus in the tumor through the loss of the whole chromosome 22, demonstrating that PM was driven by the bi-allelic loss of function of NF2." (PMID 40725095, 2025). "The increased growth observed in NF2-deficient spheroids recapitulates key aspects of the 3D tumour environment and therefore reflects tumorigenic potential, possibly mediated via enhanced YAP activity." (PMID 40744733, 2025). "Compared to the SVA, the MLD3 and especially the OA are a time-saving alternative for monitoring the tumor volume of NF2-associated VS." (PMID 39824854, 2025). "Next, we sought to explore the mechanism by which sEV’s HSP90 facilitates the proliferation of NF2-associated tumor cells and drives the transformation of MDSCs." (PMID 41149489, 2025). "In the following study, we investigated the accuracy and compared 1D and 3D-based methods for determining tumor volume in NF2-associated VS in a large patient/tumor collective." (PMID 39824854, 2025). "NF2 gene mutations are known to be more frequent in some tumor locations, including the convexities of the brain, and as more frequent in fibrous and transitional subtypes." (PMID 40447281, 2025). "Including the tumor component in the IAC is essential for assessing NF2-associated tumors, as small tumors are often initially present, particularly in children, and require close monitoring." (PMID 39824854, 2025). "All five patients with NF2 that had an identifiable germline variant also had a second NF2-related pathogenic hit in the tumor." (PMID 39941762, 2025). "Compared to mice receiving sham surgery, the CPA tumor-bearing (TB) mice had substantially higher levels of Gluc bioluminescence in their blood 12–14 days after grafting of Nf2-deficient Schwann cells." (PMID 39923035, 2025). "Our proteomic analysis of NF2-deficient tumours revealed the upregulation of Annexin-3, impacting cell proliferation." (PMID 40562609, 2025). "We found the presence of two subgroups within the grade 1 NF2-deficient tumours using proteomics and revealed a correlation to distinct genetic features." (PMID 40562609, 2025). "In summary, the Hippo signaling pathway is activated by the loss of NF2 activity, which encourages tumor growth and medication resistance." (PMID 40227645, 2025). "NF2-related schwannomatosis (NF2) is associated with various tumors of the central and peripheral nervous system." (PMID 39762911, 2025). "The FGFR2 gene is involved in the activation of the RAS–MAPK and PI3K–AKT pathways, and the NF2 tumour suppressor gene is typically mutated in most nervous system tumours." (PMID 41573648, 2025). "Schwann cells in NF2-SWN lose gene expression of NF2, leading not only to tumorigenesis and tumor expansion, but also to the loss of their repair capacity." (PMID 40895102, 2025). "Cytogenetic and molecular analyses reveal that the loss of chromosome 22, where the NF2 gene is located at 22q12.2, is a primary event in the early development of these tumours." (PMID 39316249, 2025).
tumor (continued). "Furthemore, substantial clinical heterogeneity exists among patients with NF2, including variability in genetic mutations, age of onset, tumor multiplicity, and associated neurological deficits." (PMID 41085808, 2025). "Even more, the same gene therapy caused tumor regression and prevented tumor-associated pain in another NF2 xenograft model." (PMID 40940747, 2025). "The epidemiology of NF2-SWN has only been possible to delineate after the separation of NF2-SWN from the much more frequent nerve sheath predisposing tumour condition NF1." (PMID 41160189, 2025). "NF2 is a tumor suppressor on chromosome 22q12 encoding for the Merlin protein that plays an inhibitory role in the FAK, MAPK, and PI3K/Akt/mTOR signaling pathways that regulate cellular activity." (PMID 40149634, 2025). "Neurofibromatosis type 2 related Schwannomatosis (NF2-SWN) is an autosomal dominant disorder caused by mutations in the NF2-SWN tumor-suppressor gene on chromosome 22." (PMID 40842873, 2025). "Because there are hundreds of mutations in the inhibitory gene of NF2 tumors, it can manifest as neurosheath tumors of the central and peripheral nervous systems, multiple meningiomas, ventricular meningiomas, and other related forms." (PMID 40852360, 2025). "CDKN2A/B homozygous loss was found in one grade 3 NF2-mutated tumor, while hemizygous loss was detected in three grade 2 cases." (PMID 40951339, 2025). "Loss of NF2 function can activate mTORC1 through integrin signaling, promoting tumor cell proliferation and PM cells with NF2 loss exhibit sensitivity to mTOR inhibitors, such as rapamycin." (PMID 40904706, 2025). "NF2 is a tumor suppressor that encodes for the Merlin protein, which is involved in cytoskeleton stabilization and cadherin cell attachment." (PMID 40168046, 2025). "The most prevalent off‐target alteration after 6 months of first‐line alectinib treatment was the NF2 mutation, a tumor suppressor in the PI3K/mTOR/Akt pathway that encodes for the merlin protein." (PMID 40168046, 2025). "As with most tumor-suppressor genes, most mutations in NF2 were predicted to truncate (by nonsense or frameshift) or shorten (by incorrect splicing) the protein product." (PMID 39941762, 2025). "In summary, our findings suggest that NF2-EVs can intricately influence tumor progression and immune responses in NF2-associated tumors through the transfer of HSP90." (PMID 41149489, 2025). "Some grade 1 tumours exhibit increased clinical aggressiveness, with the biallelic mutation of NF2 being the most frequently reported." (PMID 40562609, 2025). "Often NFII patients are heterozygous for NF2 loss-of-function in many of the cells in their bodies, with loss or mutation of the remaining NF2 allele leading to tumor formation in some cells." (PMID 38879607, 2024). "The genomic distribution of mutations was similar for patients with NF2 germline mutations and patients with mutations only detected in the tumor." (PMID 38265489, 2024). "Paradoxically, after conducting exome sequencing of multiregional tumor samples, evidence has shown that loss of NF2/22q is preferred as a late clonal event in mesothelioma." (PMID 38879686, 2024). "NF-2 is a tumor suppressor gene located on chromosome 22q12 that encodes the Merlin protein, which plays a crucial role in stabilizing the cell membrane’s cytoskeleton." (PMID 38611661, 2024). "These YAP1 fusions constitute an alternative to NF2 loss and are oncogenic when expressed in mice, suggesting that they are the likely tumor-initiating events and oncogenic drivers in these tumors." (PMID 38571886, 2024). "NF2-related Schwannomatosis (NF2-SWN) is a dominantly inherited neoplasia syndrome resulting from a germline mutation of the NF2 tumor suppressor gene." (PMID 38893082, 2024).
tumor (continued). "NF2 encodes for merlin, a tumor suppressor and member of the moesin–ezrin–radixin family of membrane-cytoskeleton proteins." (PMID 38610930, 2024). "NF2 encodes a tumor suppressor, moesin–ezrin–radixin-like protein (Merlin), which regulates cell survival and proliferation and is also involved in intercellular adhesion." (PMID 38739347, 2024). "Most current studies for progressive NF2-associated VS define success of a treatment based on tumor shrinkage." (PMID 38372904, 2024). "This suggests that NF-2 copy number loss is associated with an increased risk of a higher tumor grade." (PMID 38611661, 2024). "For example, in the E-cadherin-neurofibromin 2 (NF2-Hippo pathway, the deficiency of tumor suppressors such as NF2 renders cancer cells or tumors susceptible to ferroptosis." (PMID 38428031, 2024). "As a tumor suppressor gene, NF2 plays a distinctive role in associated tumors, influencing disease progression, therapeutic approaches, and patient prognosis." (PMID 38879686, 2024). "NF2-related schwannomatosis (NF2) is a rare autosomal dominant tumor predisposition syndrome caused by mutations in the NF2 tumor suppressor gene located on chromosome 22." (PMID 38672561, 2024). "For instance, NF2, which encodes Neurofibromin 2 (NF2/Merlin), serves as a tumor suppressor that links external signals to intracellular communication, residing in the plasma membrane, cell cortex, and cytoskeleton." (PMID 39544291, 2024). "NF2 mutants’ loss of tumor suppressor activity is thought to be related to the Hippo signaling pathway activity within these tumor tissues." (PMID 39796693, 2024). "Although homozygous loss of Nf2 causes early mortality, hemizygous or heterozygous loss of Nf2 results in a tumor spectrum different from that seen in the human counterparts." (PMID 39415595, 2024). "When NF2 is mutated, the Hippo tumor suppressor pathway is inactivated, leading to activation of the downstream oncogenic transcription factors YAP and TAZ." (PMID 38879607, 2024). "In the NF2 gene, a C>T nonsense (stop gained) mutation was detected in the primary tumor (M1-T) and lung metastases (M3-T) at variant allele frequency (VAF) estimates of 32% and 100%." (PMID 39935847, 2024). "Given the less predictable growth pattern of NF2-associated VS, the proportion of patients with NF2 who will potentially lose benefit from CI caused by tumor regrowth and will require ABI for hearing rehabilitation remains to be determined." (PMID 39442262, 2024). "This study also identified that the “en plaque” growth pattern, typically seen in tumors with a high tumor grade, is associated with NF-2 copy number loss." (PMID 38611661, 2024). "The NF2 gene, which encodes the Merlin protein, functions as a tumor suppressor and serves as a key negative regulator of the Hippo pathway." (PMID 38499647, 2024). "Information on the NF2 mutation status was available for 140 cases, either as sequencing result of tumor material (n = 134) or from clinical records about clinically or genetically confirmed NF2 (n = 6)." (PMID 38265489, 2024). "NF2 deficiency leads to a tumor milieu characterized by immunosuppression, which is orchestrated by multiple mechanisms." (PMID 38879686, 2024). "Functional genomic screening in NF1-mutant tumor cells reveals NF2 loss and PAK activation underlie selumetinib resistance, and we find that concurrent MEK and PAK inhibition is effective in vivo." (PMID 38216572, 2024). "Nevertheless, it was found that patients with NF2-related VS were at a substantially greater risk of experiencing tumor progression, cranial nerve dysfunction, and vestibular symptoms compared to patients with a sporadic VS." (PMID 36975476, 2023). "Although the relatively small sample size probably impacted this NF2-associated transcriptomic heterogeneity, it still provided some evidence for the vital tumor-shaping role of NF2 alteration in FH-RCC." (PMID 37131267, 2023).
tumor (continued). "Vestibular schwannomas are benign tumors of the eighth cranial nerve, caused by mutations in the NF2 gene encoding the tumor suppressor, merlin." (PMID 37345155, 2023). "Our study shows that this loss of 1p is present in the pre-progressed and post-progressed tumour and is uniformly associated with NF2 mutated tumours." (PMID 36882706, 2023). "Biallelic NF2 mutations cause tumor formation in the nervous system represented by vestibular schwannomas, meningiomas, and ependymomas, frequently accompanied by hearing loss, dizziness, and neuropathies." (PMID 37280085, 2023). "Silencing YAP/TAZ in NF2-deficient tumors induces tumor regression by increasing mitochondrial respiration, reducing glycolic-dependent growth, and causing the accumulation of reactive oxygen species (ROS) and consequent oxidative stress-induced cell death." (PMID 37190141, 2023). "One tumour from patient G had two NF2 variants co-occurring on the same sequencing reads suggestive of a complex variant." (PMID 36882706, 2023). "CROS, BiCROS, BAHS, CI, and ABI are all feasible options in patients with sporadic VS and NF2 when appropriately selected to address the severity, type of patient’s hearing loss, and integrity of the cochlear nerve after tumor resection." (PMID 37218842, 2023). "A combination of Bcl-2 and YAP inhibitors demonstrated a synergistic effect, substantially reducing tumor area and invasiveness in Nf2-KO S1M cells, emphasizing the potential therapeutic value of this combination in NF2 deficient GC." (PMID 37730636, 2023). "Higher S100 frequency was independently associated with female gender (p = 0.0003), NF2 (p < 0.0001), tumor location (p < 0.0001) and lower WHO CNS grade (p = 0.0133)." (PMID 35838837, 2023). "Cellular NF2 loss upon physiological stiffnesses analogous to the tumour niche drive YAP/TAZ‐dependent anchorage‐independent growth." (PMID 36740402, 2023). "The neurofibromatosis type 2 gene (NF2) encodes a tumor suppressor of Moesin–Ezrin–Radixin-Like Protein (Merlin)." (PMID 37371090, 2023). "The most common among these are inactivation of NF2 (moesin-ezrin-radixin like (MERLIN) tumor suppressor), followed by mutations in TRAF7 and KLF4, with the latter two being associated with more benign clinical courses." (PMID 36641486, 2023). "Molecular analysis revealed heterogeneity across patients, however broadly there were three groups; NF2 mutated tumours, non-NF2 mutated tumours and tumours with a NAB2-STAT6 inversion." (PMID 36882706, 2023). "Approximately half of all MM tumours contain mutations in the gene encoding the tumour suppressor protein neurofibromatosis type 2 (NF2)." (PMID 37469419, 2023). "CNA profiling shows frequent alterations in NF2 mutated tumours compared to non NF2 mutated tumours." (PMID 36882706, 2023). "ERM protein family members have been linked to cancer; however, NF2 tumor suppressor activity was initially characterized in flies and mice, and then in mammalian cell models." (PMID 37280085, 2023). "They develop after biallelic inactivation of the NF2 gene, which encodes a tumor suppressor called merlin." (PMID 37345155, 2023). "In sporadic VS as well as NF2 patients with VS, hearing loss as a result of the tumor or therapy can influence their quality of life significantly." (PMID 37218842, 2023). "In this subset of patients, they found that the TERT promoter mutation was found in both the lower and higher-grade tumour, and in both NF2-mutated and NF2-wildtype tumours." (PMID 36882706, 2023). "The NF2 gene encodes a 70-kDa protein called merlin, mainly acting as a tumor suppressor and participating in diverse cell signaling pathways." (PMID 37217995, 2023). "Within this tumor, the deletion of the long arm of chromosome 22 effectively resulted in reduction to homozygosity of the NF2 frameshift variant but loss of the CHEK2 mutant allele, resulting in enhanced representation of the wild-type allele in the tumor." (PMID 36980535, 2023).
tumor (continued). "Patient G had four tumours with three different NF2 somatic mutations, all of which were present in the pre-progressed tumours." (PMID 36882706, 2023). "With respect to 1p loss, 21.4% of NF2 patients’ and 53.3% of sporadic NF2-altered tumour showed 1p loss (p = 0.07)." (PMID 37752594, 2023). "Mutations in the amino-terminal domain of NF2 proteins are associated with early tumor onset with more severe disease progression." (PMID 37217995, 2023). "Germline mutations in this gene cause the hereditary tumor syndrome neurofibromatosis type 2 (NF2), which is primarily characterized by an enhanced predisposition to developing tumors of the central and peripheral nervous system." (PMID 37174657, 2023). "Therapy for NF2 generally includes monitoring or symptomatic tumor treatments, e.g., surgical excision or radiation for tumor bulk causing mass effect." (PMID 38058737, 2023). "A comprehensive French study genetically profiled NF2 patient blood and tumor DNA and revealed additional mutations in SMARCB1 and LZTR1 in 65% of patients." (PMID 38058737, 2023). "The mutation incidence in tumor samples was as follows: NF2 R57* (15/27), PIK3CA E545K (13/27), BRAF Hotspot mutations (10/27), SMO L412F (9/27), SMO W535L (7/27), with varying mutant allele frequencies represented by the dot sizes." (PMID 38259646, 2023). "A common mutations in the NF2 gene (c.240G > A) was detected in the primary tumor tissue and in JEI-002, indicating that the immortalized cell line retained most of its original tumor characteristics." (PMID 35359340, 2022). "Parasinoidal (26/60) was the most common location in NF2 mut/loss group, while NF2 wild tumours were more likely in skull base locations (25/45)." (PMID 36267986, 2022). "Tumours associated with neurofibromatosis type 2 (NF2) are often bilateral and occur at a younger age." (PMID 35397067, 2022). "This study revealed that QDSJ decoction exerts a multitarget antitumor effect on NF2-associated VS by increasing cell apoptosis, reducing cell proliferation, and normalizing tumor blood vasculature." (PMID 36059985, 2022). "A tumor suppressor, NF2 encodes a cytoskeleton scaffold protein involved in cell proliferation and apoptosis." (PMID 34846640, 2022). "In summary, we show that QDSJ decoction suppresses tumor growth and improves vascular normalization of NF2-associated VS." (PMID 36059985, 2022). "In our series, four patients (8%) experienced local tumor recurrence with three of these cases harboring a NF2 mutation and with tumor calcifications." (PMID 35943573, 2022). "Mer, an important inhibitor of YAP/TAZ, is encoded by the neurofibromatosis type 2 (NF2) tumour suppressor locus." (PMID 36362947, 2022). "The NF2 associated tumours are similar to sporadic tumours but are described as having more Verocay bodies and more foci of high cellularity." (PMID 35397067, 2022). "NF2 is caused by pathogenic variants in the NF2 gene that encodes merlin, an actin-associated tumor suppressor." (PMID 35875610, 2022). "Multivariate analysis performed using factors with p < 0.25 in the univariate analysis further indicated that NF2 alteration/22q loss was associated with tumor recurrence (HR, 13.1; 95% CI, 1.5–111; p = 0.019)." (PMID 35804955, 2022). "Separately, “high” methylation levels were found in tumors from older patients, those with increased somatic mutation burden, higher tumor grade, convexity location, and NF2 mutations." (PMID 34846640, 2022). "Surprisingly, recent studies have revealed that NF2 mutations are also capable of regulating tumor immunity." (PMID 36497453, 2022). "Several preclinical and clinical trials have demonstrated that antiangiogenic therapies can inhibit NF2-associated VS tumor growth and postpone the related hearing loss." (PMID 36059985, 2022). "The potential to proliferate and retain motility within a cell-dense region of tissue would also likely facilitate tumour growth and metastasis on loss of NF2." (PMID 35119068, 2022).